TLR4 (toll like receptor 4)
Diseases named in the same sentence as TLR4 in open-access papers (continued):
Sharing a sentence is not in itself a finding about the gene and the disease.
cancer (continued). "Toll-like receptor 4 (TLR4)-induced monocyte inflammation is important for induction of IL21+ TFH-like cells, which operate in IL21-IFNγ-dependent pathways to induce plasma cell differentiation and thereby create ideal conditions for M2b macrophage and cancer progression." (PMID 33365025, 2020). "Moreover, silencing of TLR4 but not TLR2 markedly recovered disialyl Lewisa or sialyl 6-sulfo Lewisx expression on the cancer cell surface." (PMID 32050430, 2020). "However, the mechanism of AMPKαl on cancer progression through TLR4-mediated autophagy activation has not yet been investigated." (PMID 33172060, 2020). "Examples of well-known TLR ligands that have been assessed in cancer vaccines are Pam3CSK4 and Pam2Cys for TLR-2/1 and -2/6 respectively, poly(I:C) for TLR-3, LPS and monophosphoryl lipid A (MPLA) for TLR-4, imiquimod and other imidazoquinolines for TLR-7/-8, and CpG-B for TLR-9." (PMID 32117911, 2020). "However, TLR4 is not confined to immune cells but is found in numerous cancer cells and evokes pathological processes, including angiogenesis‐driven HCC promotion." (PMID 32144747, 2020). "Previous studies suggested that TLR4 expression might be the link between H. pylori infection and cancer, and this expression pattern is not significantly changed after the eradication of bacteria." (PMID 29670922, 2018). "TLR4 ligation by PTX could activate downstream signaling via NF-κB and MAPK that promote pro-inflammatory mediators i.e. IL-6, IL-8, MCP-1, VEGF and XIAP, the functions of which have been reported to enhance cancer progression and drug resistance." (PMID 29486738, 2018). "However, LPS, the natural ligand of TLR4, is not applicable for cancer immunotherapy due to severe systemic toxicity." (PMID 29079801, 2017). "Our data suggest that HMGB1 released from cancer cells under glucose deprivation is involved in stimulating colonic myofibroblast migration and invasion and that this occurs through the activation of RAGE and TLR4, resulting in the activation of the MAPK and PI3K signalling pathways." (PMID 26979829, 2016). "Although RNF216 has several interaction partners, such as TLR4, RIP1, TRAF3 and BECN1, our data showed that only BECN1 was significantly upregulated in CRC cells in response to RNF216 knockdown, supporting that RNF216 contributes to cancer development by regulating autophagy." (PMID 27203674, 2016). "Furthermore, these authors found TLR2 and TLR4 overexpression in intestinal metaplasia, independent of the H. pylori status, and in the dysplasia/cancer sequence." (PMID 25873761, 2015). "As the expression of TLR4 has been reported on a large number of tumors, BLS signaling via TLR4 could make a notable contribution to the success of cancer treatment when coadministered with other cancer vaccines or treatments like radiation or chemotherapy." (PMID 25973756, 2015). "We identified Toll-like receptor 1 (TLR1), TLR2, TLR4 and TLR8 gene expression levels and downstream gene, i.e., interleukin-6 (IL-6), IL-8, interferon-α (IFN-α) and myeloid differentiation primary-response protein-88 (MyD88), expression levels in CRC patients and in cancer cell lines." (PMID 25547486, 2014). "We followed the villin-TLR4 mice up to 64 weeks and none developed carcinomas." (PMID 23691015, 2013). "It is therefore not too surprising that TLR4 activation affects not only the immune response against invading Gram-negative bacteria but is also involved in chronic inflammation, autoimmune diseases, and malignancies." (PMID 22110526, 2011). "However, it is important to note that the role of TLR4 signaling in cancer is complex and context-dependent, and its nonselective inhibition may exert both positive and negative effects on the immune response." (PMID 37345131, 2023).
cancer (continued). "Apart from the hypothesized TLR4-mediated endocytosis, XOS can enter cells via plasma membrane transporters and influence specific intracellular targets including the glutathione antioxidant system, which is a major regulator of redox state in normal and cancer cells." (PMID 36142342, 2022). "Finally, we suggest that the effects of opioids on non-opioid receptors, including but not limited to TLR4, may offer novel insights into the role of opioids on cancer in the future." (PMID 35004315, 2021). "Indeed, dendritic cells lacking TLR-4 or its downstream adaptor molecule Myd88 could not present antigen from dying tumor cells and did not elicit a T-cell mediated anti-cancer immune response in mice." (PMID 25688334, 2015). "Through the interaction with bacterial lipopolysaccharide (LPS) on the outer membrane of Gram-negative bacteria, it activates Toll-like receptor 4 (TLR4) on the host cell surface, inducing an immune response of T cells against cancer cells." (PMID 40940924, 2025). "In contrast, several PRGs, such as TLR4 and PYDC1, showed miscellaneous cancer-type-specific patterns that have not been previously characterized." (PMID 35008400, 2022). "Assessing putative cell surface receptors (TLR2 and TLR4) binding with extracellular HMGB1, we found that TLR2, but not TLR4, was upregulated in the CD133− cancer cells when treated with HMGB1+ irradiation cells or rhHMGB1." (PMID 31558702, 2019). "Surprisingly, even though the previous study suggested that SN extracts can reduce TLR-4 activities, the level of TLR-4 in cancer cells was not affected by SN extracts or in combination with gemcitabine." (PMID 31521140, 2019). "Specifically, by stimulating TLR4 signaling, gram-negative bacteria induced robust IL-33 expression in NSCLC cells, facilitating cancer metabolic reprograming and development of cancer stem cell properties." (PMID 29568370, 2018). "However, it is not known whether or how IgG interacts with TLR4 signaling in cancer cells." (PMID 25179302, 2014). "In undifferentiated G3 carcinoma, staining for TLR3 and TLR4 was not detectable, strengthening our findings of low TLR3 and TLR4 mRNA abundance in G3 carcinoma." (PMID 18775079, 2008). "Moreover, although not in the cancer context, HMGB1 was shown drives upregulation of P-gp at the blood–brain barrier following cerebral ischemia via the related TLR4/NF-κB pathway." (PMID 41465435, 2025). "TLR4 signaling has been shown to lead to the accumulation of HIF-1α, a key transcriptional regulator of CAMs, and the IRE1α-XBP1 signaling axis enhances HIF-1α transcriptional activity without affecting HIF-1α protein levels in cancer cells." (PMID 36475773, 2023). "Interestingly, we found that the 5hmC of the toll like receptor 4 (TLR4) gene was not statistically different between cfDNA and gDNA from cancer patients, indicating consistency between cfDNA and gDNA." (PMID 37628686, 2023). "In this sense, bacterial lipopolysaccharide (LPS), a major component of the outer membrane in Gram-negative bacteria, may activate the host’s cell surface Toll-like receptor 4 (TLR4), thus triggering immune T cell-mediated response against cancer cells." (PMID 36672391, 2023). "The enhanced phosphorylation of NFκB in CRC cells after palmitic acid treatment suggests that the activation of the TLR4 signaling pathway is, at least in part, due to the enhanced TLR4, MyD88, and TIRAP expressions in the cancer cells but not a direct binding of palmitic acid to the TLR4 protein." (PMID 34385421, 2021). "Furthermore, we provided new insights that CXCL10 through TLR4, instead of CXCR3, mobilized monocytic MDSCs, but not granulocytic MDSCs, to the liver for facilitating cancer recurrence using CXCL10−/−, CXCR3−/− and TLR4−/− mice." (PMID 33990548, 2021). "However, the possible involvement of TLR4 and ECM remodeling in cancer cachexia was not a focus of this study and needs further analysis." (PMID 30575787, 2018).
cancer (continued). "It is therefore of great interest to examine the potential role of overexpressed HAPLN1 as a matrikine, rather than an ECM structural element, in other cancer types and whether these malignancies also employ a CH60/TLR4 complex to detect a HAPLN1 matrikine to promote pro-tumorigenic properties." (PMID 36625202, 2023). "Since cancer cell membrane-expressed PD-L1, not PD-L1 in cytoplasm, has biological significance, and is related to PD-L1 inhibitor treatment outcomes, our study shows that PAUF is unlikely to impact the PD-1 and PD-L1 treatment outcomes, even if it can change PD-L1 level in cytoplasm via TLR4." (PMID 36232715, 2022). "The HMGB1 released by ferroptotic cancer cells activated innate immune cells and triggered an inflammatory response that was dependent on HMGB1 binding to the cognate receptor, advanced glycosylation end product-specific receptor (AGER), and not toll-like receptor 4 (TLR4) on macrophages." (PMID 35065965, 2022).
bacterial infection (338 papers, 2005 to 2026). "During bacterial infections, TLR-4 senses toxins or lipopolysaccharides, causing pro-inflammatory reactions that aid in eliminating invasive pathogens." (PMID 39452787, 2024). "The major cause of ALI is a bacterial infection, which is recognized by alveolar macrophages via Toll-like receptor 4 (TLR4)." (PMID 32256655, 2020). "Compared to wild-type mice, there was an increased bacterial load in both these deficient mouse strains and an altered IIR, although TLR4–/– mice were more susceptible to bacterial infection." (PMID 33042124, 2020). "CD11b is a negative regulator for TLR4 signaling and CD11b-deficienct mice were susceptible to bacterial infection." (PMID 28529765, 2017). "To summarize, a combined TLR3- and TLR4-stimulation, representing a concomitant viral and bacterial infection, caused an AHR that was further exaggerated during an on-going allergic inflammation." (PMID 26494305, 2015). "To conclude; a combined TLR3- and TLR4-stimulation, representing a concomitant viral and bacterial infection, causes an AHR that is further exaggerated during an ongoing allergic inflammation." (PMID 26494305, 2015). "TLR4 polymorphisms have been proposed to affect the probability of disease either through increased susceptibility for bacterial infections or through altered inflammatory states." (PMID 26161647, 2015). "TLR4 activation of epithelial RelA was implicated in the chemokine gene expressions and neutrophil recruitment upon bacterial infections." (PMID 25905673, 2015). "Toll like receptor (TLR)-4 is classically associated with myeloid cells and works as signaling receptor through which the cells sense bacterial infections." (PMID 25254631, 2014). "For example, the degradation of TLR4 observed in monocytes is associated with LPS tolerance, helping the animal survive bacterial infection." (PMID 24025421, 2013). "Experimental investigations revealed that TLR4 gene mutations were associated with low response to viral and bacterial infection and therefore led to a reduction in the innate immune response and inflammation." (PMID 21559380, 2011). "TLR4-deficient mice showed lower response to viral and bacterial infection than did wild-type mice, which suggested that TLR4 activation pathway can initiate innate immune responses to both bacterial and viral pathogens." (PMID 21559380, 2011). "For example, Toll-like receptor 4 (TLR4) gene polymorphisms may affect the immune response of newborns to bacterial infections." (PMID 41195176, 2025). "SNP mutations in TLR4 influence the recognition of bacterial infections." (PMID 41007947, 2025). "However, they found impaired LPS-induced cytokine synthesis in CKD patients predisposed to bacterial infections, with each cytokine response showing a significant correlation with TLR4 expression in monocytes." (PMID 38922137, 2024). "TLR4 is crucial for detecting and responding to bacterial infections, and blocking TLR4 signaling may increase susceptibility to bacterial infections." (PMID 37896221, 2023). "This not only was confirmed by a study in which mice given ventilation support increased their risk of secondary bacterial infection, but also suggests that TLR4 could indirectly be a potential therapeutic target, via treatment with TLR4 antagonists." (PMID 37513775, 2023). "Beyond the initial responses to viral RNA infection there may be further amplification of inflammatory responses by secondary bacterial infections or by pattern associated molecular patterns in damaged tissues that lead to activation of TLR4 signalling." (PMID 34952919, 2021). "In addition, given that another SNP, namely, the rs4986791 SNP (T399I) of the TLR4 gene, is also associated with bacterial infection, further validation of the association of rs4986791 SNP in HIV-infected patients should be performed in future studies." (PMID 33396586, 2020).
bacterial infection (continued). "In the murine model of trauma hemorrhage followed by resuscitation with stored blood, increased bacterial infection susceptibility and severity are associated with free heme in a TLR4-dependent manner as scavenging heme by Hpx or deletion of TLR4 prevents mortality." (PMID 33374506, 2020). "Additionally, bacterial infections in mouse models have been shown to cause placental inflammation and poor pregnancy outcomes in a TLR4-dependent manner." (PMID 29440369, 2018). "In addition to polymorphisms, TLR4 expression is regulated in diseases such as bacterial infection and tissue damage." (PMID 25139109, 2014). "Septic patients with TLR-4 polymorphism had increased risk of bacterial infection." (PMID 25412934, 2014). "Lumican-deficient (Lum−/−) mice and macrophages are impaired in TLR4 signals; raising the possibility that lumican may regulate host response to live bacterial infections." (PMID 23358433, 2013). "Moreover, a significantly higher incidence of bacterial infection has been reported in intensive care unit patients with TLR4 mutations." (PMID 22662179, 2012). "For an anti-TLR4 antibody to be successful in preventing the inflammatory response to cobalt ions it is essential that the immunological response to LPS is maintained or else there is a high risk of overwhelming bacterial infection and potentially lethal septic shock." (PMID 26840091, 2016). "Activation of TLR4 promotes iNOS expression and enables cells to secrete more NO to promote bacterial infection." (PMID 41596253, 2026). "This study aimed to examine the association between TLR4 rs2149356, LTA rs2229094 and RFP175 rs1585110 polymorphisms and the risk of invasive bacterial infections in infants under three months of age." (PMID 41450988, 2025). "TLR2 and TLR4 play a key role in the development of an inflammation in responseto a bacterial infection." (PMID 40264577, 2025). "These were predominantly enriched in the Toll-like receptor signaling pathway and bacterial infection-related genes, such as TLR4, JUN, and TNFSF10." (PMID 41375527, 2025). "At the beginning of a bacterial infection, TLR4 recognize LPS and along with its co-receptor MD2 forms a complex on the surface of cells that binds to LPS facilitated by CD14." (PMID 40725160, 2025). "TLR4-dependent innate immune system activation is, therefore, a crucial step in regulating the response to bacterial infections." (PMID 40564217, 2025). "This suggests that berberine and carvacrol treatment inhibited the mRNA expression of TLR2 and TLR4 in bacterial infections." (PMID 40431224, 2025). "Oxidative stress, TLR4/Myd88/NF-κB related inflammatory signaling, and apoptosis are important body responses in response to bacterial infection." (PMID 40239311, 2025). "Toll-like receptor 4 (TLR4) serves as a crucial inflammatory marker; for instance, during bacterial infection, TLR4 can induce inflammation." (PMID 40427234, 2025). "TLRs were all found to be expressed in GMCs, with TLR4 as the dominant one in our study, suggesting that GMCs carry the capability of inducing an inflammatory response in bacterial infection." (PMID 41376641, 2025). "CD11b increased expression has been shown in microglia after bacterial infection and neurodegenerative conditions, but is thought to be a immunomodulatory receptor acting on TLR4 pathway." (PMID 41487996, 2025). "The release of LPS by E. coli during bacterial infections allows it to enter the cells independently of TLR4 signaling." (PMID 40552401, 2025). "TLR4, a critical regulator of inflammatory responses, plays essential roles in viral and bacterial infections." (PMID 40572089, 2025). "Consistent with previous research findings, the expression of TLR4 significantly increases after viral or bacterial infection, and the expression of its downstream related indicators also markedly rises, which can lead to more severe pathological damage." (PMID 40572089, 2025).